CD4 (CD4 molecule)
Diseases named in the same sentence as CD4 in open-access papers (continued):
Sharing a sentence is not in itself a finding about the gene and the disease.
infection (continued). "To that end, we explored the role of infection in depletion of CD4+ T cells in the lung parenchyma of SIV-infected macaques from the early to later stages of infection." (PMID 25933119, 2015). "S. aureus antigen-specific IFNγ-producing CD4+ (Th1) cells are expanded in both humans and mice following infection, and these cells are definitively protective in mice." (PMID 26539822, 2015). "According to the previous report, the major source of IFN-γ in P. berghei ANKA infection is CD4+ T-cells at the site of infection." (PMID 26466097, 2015). "Following infection of CD4+ T-cells co-cultured with each APC subpopulation, post-integration latency followed a similar pattern to that observed for total latency, but at a lower frequency." (PMID 26362311, 2015). "One such mechanism is the DC-mediated trans-infection pathway, whereby DCs transmit captured virus to CD4+ T cells." (PMID 25760631, 2015). "More recent studies have suggested that IL-27 also has the function to inhibit immunopathology via downregulation of active CD4+ T cells during infections, particularly with intracellular protozoan parasites." (PMID 26222157, 2015). "The proportion of CD4+CD25+ cells among all the CD4+ cells in the thymus decreased markedly after infection with either the Harbin-1 strain or the Ts strain." (PMID 25803101, 2015). "The lamina propria CD4+ T cells that are exposed to commensal bacteria were reported to increase the productive infection in the lamina propria CD4+ T cells in vitro by enhancing T cell activation." (PMID 25806508, 2015). "Dendritic cells (DC), which are unrelated to the stromal derived FDC, are also capable of recycling HIV and form a source of infection for CD4 T cells." (PMID 26623655, 2015). "A particular role for CD4+ T cells has also been shown in reducing viral transmission at time of primary infection during pregnancy." (PMID 26363059, 2015). "During the first 12 months of infection, subjects with higher baseline B-cell counts had persistently high CD4+ T-cell counts and low viral loads." (PMID 26436092, 2015). "We have previously shown that the chronic phase of infection with P. chabaudi generates memory-phenotype specific CD4 T cells, and maintains excellent protection from re-infection." (PMID 26646149, 2015). "HIV-1 enters DCs by both receptor mediated endocytosis and macropinocytosis, however it is the macropinocytosis pathway that contributes to DC-mediated HIV-1 trans-infection of CD4+ cells, revealing a role of macropinocytosis in propagating HIV infection." (PMID 25688210, 2015). "In patients with chronic HCV-1/6 infection, univariate analysis showed that age (p = 0.005), CD4 count (p = 0.08), HCV RNA level (p = 0.006), IL28B genotype (p = 0.03), and RVR (p = 0.003) were associated with SVR." (PMID 26616669, 2015). "By 8 days after infection, however, a higher percentage of the CD4+ T cells from old mice were phenotypically TFH, and adult and old mice had equivalent numbers of GC B cells." (PMID 26204259, 2015). "In the current study, all of the HIV+ subjects showed a low level of infection (<20 copies) in their circulating CD4 T cells as expected." (PMID 26623655, 2015). "In this study, we systematically examined the infected cell types and the depletion of CD4+ T cells in the lungs of SIV infected rhesus macaques in the very early to later stages of infection." (PMID 25933119, 2015). "The number of CD4+ regulatory T cells before infection was similar between TTR-NP1/0 and TTR-NP mice in both the spleen and liver." (PMID 28210682, 2015). "The Research Topic presented here, “CD4 T cell differentiation in infection: an amendment to Th1/Th2 axiom” is a collection of reviews that cover the most recent progress on Th effector choice mechanisms in various infection models." (PMID 25972870, 2015). "Overall, FLUAVsw-specific cytokine+CD4+ T cells were found to be increased from one (#7, #8) or two (all other animals) weeks after primary infection." (PMID 25971313, 2015).
infection (continued). "STDs increase the concentration of dendritic cells and CD4 T-cells in the genito-anal region, which is the most usual site of STDs infection." (PMID 26039757, 2015). "Analysis of the mean HIV-1 integrated DNA in CD4+ T-cells from individuals under antiretroviral therapy (ART) revealed less than 1100 copies per 106 cells, indicating infection frequencies < 0.2% of CD4+ T-cells." (PMID 25886562, 2015). "Early studies in the SIV model demonstrated that, regardless of the route of infection, the intestinal tract is the primary target for SIV replication, amplification, and marked CD4+ T cell depletion in the earliest stages of infection." (PMID 26695751, 2015). "Unexpected results are that the infection rate changes as the disease progresses even in CD8+/CD4+/NK cells from the same H7N9 patients, when the assay was performed on the same day." (PMID 25967273, 2015). "Prodigious numbers of resting memory CD4+ T cells become infected in lymphoid tissues and blood and large amounts of circulating progeny virions are produced during this phase of the infection." (PMID 25996507, 2015). "CD4+ TM cells participate in the responses against secondary infections by potentiating antipathogen effector mechanisms of innate immunity, antibody production, and CD8+ T cell cytotoxicity." (PMID 26509177, 2015). "At day 3 post-infection, surface expression levels of tetherin and CD4 were quantified by flow cytometry." (PMID 26554585, 2015). "L'immunodépression avancée se traduit cliniquement par un stade clinique (selon l'OMS) avancé et la survenue des infections opportunistes, et biologiquement par l'augmentation de la charge virale et de la baisse du taux de CD4." (PMID 26600917, 2015). "Recently, SAMHD1 was identified in macrophages, DCs and resting CD4+ T cells and shown to block infection with HIV-1." (PMID 26121641, 2015). "HIV-1 targets for infection and subsequent depletion cells of the immune system that play key roles in the defense against pathogens, including the Th17-polarized CD4+ T-cells." (PMID 26654242, 2015). "Panel B, R880F exhibited much higher-magnitude Gag and Env-specific CD4 T cell responses than R463F both during acute infection at ∼3 months post-infection." (PMID 25569444, 2015). "An analogous pattern of CD69 expression was seen in adult and old CD4+ T cells, although a smaller subset of cells was activated (e.g., 31% at 2 days after infection)." (PMID 26204259, 2015). "Infection with high-risk HPV types was associated with younger age and lower CD4+ lymphocyte counts." (PMID 26100400, 2015). "CD4+Foxp3+ T-cells accumulate at sites of infection and prevent efficient clearance of infection in mice infected with M. tb." (PMID 25659138, 2015). "As far as HIV+ adults are concerned, the guidelines indicate to consider the absolute number of CD4+ T cells to monitor the infection." (PMID 25622041, 2015). "In previous reports, CD4+ and CD8+ were shown to be important T lymphocyte markers and the major histocompatibility complex (MHC) class II-restricted CD4+ T cells were essential to resolve the primary infection." (PMID 25893439, 2015). "Our data showed that infection with either lineage led to a higher expression of the activation molecule CD69 by CD4+ and CD8+ T lymphocytes as compared to media control." (PMID 26147698, 2015). "In macrophages, Nef activates a variety of signaling pathways that leads to the infection of bystander CD4+ T cells and hence expands viral reservoirs." (PMID 25835530, 2015). "In contrast, dermal CD4+ T cells from 1x mice recovered on day 4 after infection proliferated vigorously to parasite SSAP antigen, to a much greater level than in response to SC (p<0.0001)." (PMID 25974019, 2015). "First, the C19+A8, C19+E6, C27+A8, and C27+E6 dual infections were added in equal “x4” titers (determined on U87.CD4.CXCR4 cells) to PBMC cultures in the presence of high maraviroc (MVC) concentrations." (PMID 26435727, 2015).
infection (continued). "To evaluate the potential for this partial activation to contribute to cell-to-cell HIV spread, we developed two in vitro infection models using primary CD4 T cells that were either unstimulated or activated." (PMID 26539983, 2015). "Ex vivo analyzes of Tregs following PRRSV-2 infection of nine week old pigs also indicated an increase of CD4+CD8α+Foxp3+ Tregs." (PMID 25990845, 2015). "Preemptive priming of CD4 T-cell help can promote effective and rapid conversion of naïve B cells to mature antibody-secreting cells and improve protection from infection." (PMID 25629161, 2015). "Eight days after infection CD4+ and CD8+ cells had values similar to the control animals, although a slight increase of double positive cells was observed." (PMID 26469517, 2015). "In a previous screen of miRNAs expressed in LAT-KI T cells, we observed overexpression of miR-155 in LAT-KI CD4+ T cells compared to WT CD4+ T cells proliferating in response to infection by H. polygyrus or in response to transfer to an immunodeficient host." (PMID 26121028, 2015). "After in vitro infection, CD4+ cells from CNAR(+) and CNAR(-) LTNPs and uninfected macaques replicated SIV to a similar extent." (PMID 26551355, 2015). "During human infection of CHIKV CD8+ T-cells seem to be preferentially activated during the first few days of infection followed by a switch to CD4+ T-cells." (PMID 26389957, 2015). "The third scenario (ART initiation according to WHO guidelines at CD4+ count of 500cells/mm3) implied an average time of 0.67 years since infection and resulted in 14013 transmitted infections." (PMID 26302044, 2015). "The CCR5, which is expressed in lymphocytes, myeloid cells or CD4+ T cell subsets, is responsible for establishment of new infections and is dominant in the chronic phase of infection." (PMID 26481100, 2015). "At day 8 post-infection with P. chabaudi, we sorted CD4+TCRβ+Ifngyfp+Il4gfp-Il17aFP635– cells from the spleens of recipient mice." (PMID 26147567, 2015). "Retnlb-/- mice showed a selective reduction in CD4+ T cell numbers within the large bowel during infection, as compared to wildtype mice." (PMID 26285214, 2015). "Mice reconstituted with CD4+ Foxp3- T cells prior to infection showed a mean survival of 126.8 days." (PMID 26512987, 2015). "On the other hand, the amount of CD4+ T cells was higher in relation at IG infected animals at 26th days post infection." (PMID 26469517, 2015). "Our data strongly support an early Th2/systemic antibody response to polybacterial infection, demonstrated by significantly elevated serum IgG and IgM at 12 weeks of infection, supported by significantly greater numbers of Th2-promoting CD4+ splenic T cells." (PMID 26619277, 2015). "This opposed the DTH theory and suggested that a Th2 response either was ineffectual at clearing infection or led to enhanced pathology and that CD4+ Th1 IFNγ responses were a key element of protective immunity in trachoma." (PMID 26424969, 2015). "We found, after 12 months of infection, the baseline B-cell counts/percentages correlated positively with CD4+ T-cell counts (P = 0.0006 and P = 0.026) and negatively with HIV viral set points (P = 0.014 and P = 0.002)." (PMID 26436092, 2015). "CD4+ T cells from Leishmania major infected CD98hcf/f-CD4 and CD98hc+/+-CD4 mice 10 or 70 days after infection were stimulated with Leishmania major-derived antigens for three days and IFN-γ levels in culture supernatants were measured." (PMID 26444422, 2015). "In vivo studies have found that resting CD4+ T cells in lymphoid tissue harbor viral RNA, and ex vivo studies have shown that directly infecting resting CD4+ T cells from lymphoid tissue results in productive infection." (PMID 26067822, 2015). "If expected survival time after progressing to ‘low CD4’ count is the same for high and low SPVL infections, or if it is longer for low SPVL infections but only in proportion to the additional time taken to reach the low CD4 threshold, then (2.7) holds." (PMID 26609066, 2015).
infection (continued). "Results of serology-based test of recent infection combined with:Clinical data (e.g., CD4+ cell counts, HIV-1 RNA load, ART status)Measure of HIV diversityCombination of Assays can be optimized to increase accuracy." (PMID 26512688, 2015). "HeLa-CD4 cells were transfected twice (24 h apart) with either a non-targeting siRNA or siRNA targeting cullin 1, followed by infection with either DHIV-GFP WARO (Vpu+/Nef−) or DHIV-GFP (Vpu−/Nef−)." (PMID 26215564, 2015). "Activation of macrophages likely occurs at the site(s) of infection as a result of tissue migration of peripheral CD4 T-cells." (PMID 26630153, 2015). "A considerable proportion of them were in recent infection, particularly in the C cluster, and most of them were early diagnosed as indicated by the high CD4 cell count." (PMID 26270824, 2015). "This occurs in vitro by direct infection of chemokine-treated resting CD4 T cells, by spinoculation or by co-culture with dendritic cells or endothelial cells." (PMID 25573791, 2015). "The expression of PD-1 at later stages of infection for both CD4+ and CD8+ T cells was similar between the METH treated or untreated infected mice." (PMID 26322025, 2015). "Peptidoliposomes containing different combinations of the CCR5 (N-terminus and ECL2) and CD4-peptidomimetics were initially tested for their ability to inhibit infection of TZM-HeLa-β-gal target cells by R5-tropic JRFL-pseudotyped HIV-1." (PMID 26629902, 2015). "This is because more target cells lead to more abortive infection, which releases more cytokines attracting more CD4+ T cells to be infected and die." (PMID 26709961, 2015). "Natural killer cells (NKs), dendritic cells (DCs) and CD4+ T cells were also readily detected after infection, with increases in NKs noted in the BAL." (PMID 25880560, 2015). "As discussed in the Background section, the ability of mac-tropic Envs to bind CD4 efficiently and use low levels of CD4 for infection indicates that these Envs are probably more functional during entry compared to non-mac-tropic Envs." (PMID 26055104, 2015). "Our data showed a significant enhancement of infection for CD4+ T-cells by all Env+ pseudovirions by an average of >10-fold, with the three Env+ virus groups enhanced to similar extents." (PMID 25809903, 2015). "Using DN1Tg/hCD1Tg mice, we found that activation of DN1 T cells was initiated in the mediastinal lymph nodes and showed faster kinetics compared to Mtb Ag85B-specific CD4+ T cells after aerosol infection with Mtb." (PMID 26652001, 2015). "Our findings raise significant questions regarding the most commonly accepted model for the establishment of latent HIV and suggest that infection of both resting and activated primary CD4+ T cells produce latency." (PMID 26067822, 2015). "Meanwhile, the proportion of CD4+CD25+ cells in the spleen exhibited a decrease on the first day of Harbin-1 infection and then returned to a normal level relative to the PBS group by 3 dpi and 5 dpi." (PMID 25803101, 2015). "At thirty three days of infection a reduction in the number of CD4+ cells was also observed, but lower than that observed at 26 days for the IG infected mice." (PMID 26469517, 2015). "In summary, efficient infection of primary CD4+ T lymphocytes required contact-dependent, neutralizing antibody-resistant, cis-mediated virus transfer from HIV-1 infected MDM." (PMID 26186441, 2015). "Relationship between the Eg-infection and the newly identified CD4+ T cells subgroup called follicular helper CD4+ T (Tfh) cells is not reported." (PMID 26503442, 2015). "Three weeks post infection, neutropenic mice had a higher fraction of intracellular IFNγ+ CD4+ T cells in the dLN." (PMID 26020515, 2015). "As one of the hallmarks of the APOBEC3 restriction is the induction of G-to-A hypermutation in viruses, we looked for evidence of such hypermutation in integrated viral genomes nine days after infection of primary chimpanzee CD4+ T cells." (PMID 26394054, 2015).
infection (continued). "Mice were analyzed at various time points post infection to determine the ratio of CD4+/CD8+ T cells." (PMID 26034905, 2015). "This was true when analysing by year of enrolment, by CD4+ T cell count or even when dividing individuals with recent and longstanding infection." (PMID 26558396, 2015). "Analysis of viral loads revealed that depletion of CD4+ T cells during the initial phase of the infection greatly impaired viral clearance in GITRL tg mice." (PMID 25738498, 2015). "APCs also activate the TCR on CD4+ T cells and enhance CD4+ T cell migration to the site of infection through a TCR-MCHII receptor-ligand response, represented by the second term, rcd4Mb(Mbn/(Mbn + kc8n))Mb∗TCD4." (PMID 26446682, 2015). "Here, we show significant interstitial CD4+ T cell depletion in the lungs during very early infection that is sustained through 12 weeks." (PMID 25933119, 2015). "Many studies indicate that resting CD4+ T cells are refractory to productive HIV infection but can become permissive to infection after treatment with certain cytokines or chemokines that do not induce classic T cell activation." (PMID 26067822, 2015). "We find HIV-1-induced formation of VCCs is restricted to myeloid cells, and that the cytoplasmic tail of CD169 is dispensable for HIV-1 trafficking and retention within VCCs and subsequent trans-infection to CD4+ T cells." (PMID 25760631, 2015). "Infection in the GALT is extensive, reaching 60% of the mucosal memory CD4+ T cells within days post-infection and the infected cells are rapidly eliminated." (PMID 29061947, 2015). "A statistical significant four-fold faster of CD4+T cell decline and a higher rate of virological rebound in subtype D infections was found compared to other subtype infections." (PMID 26121491, 2015). "Based on a controlled PCV2 vaccination-infection experiment, the present study puts a strong focus on the role of CD4+ T cells and their potential role following vaccination and/ or infection." (PMID 25888899, 2015). "On the other hand, murine infection studies emphasize the importance of classical, CD4 IFN-γ bacterial immunity." (PMID 25862821, 2015). "In such individuals, therefore, the CD4 cell effector functions engaged were suitable to control the infection; termed HCMV controllers." (PMID 26258786, 2015). "The proportion of CD4+CD25+ cells also exhibited an immediate decrease after Ts strain infection; however, in contrast to the Harbin-1 group, this proportion returned to a normal level by 5 dpi in the Ts group." (PMID 25803101, 2015). "In this study, we investigated double infection of primary CD4+ T cells using combination reporter viruses that measure viral fusion and LTR-driven EGFP or mCherry expression." (PMID 26559763, 2015). "To test the contribution of these cells to the IL-10 produced in the early phase of infection, we measured the proportions of CD4+ Foxp3− IL-10+ T cells coexpressing IFN-γ and IL-4." (PMID 26195548, 2015). "Antiretroviral therapy promotes significant increases of IL-2+IFN-γ+- and IL-2+TNF-α+- secreting CD4+ T cells and hinders the progression from infection to active TB, while single IFN-γ+ CD4+ T cells declined significantly." (PMID 25822536, 2015). "In order to determine if PD1 was required in vivo for the development of hyporesponsiveness, mice were administered anti-PD1 MAb throughout the infection process, and the proliferation of CD4+ T cells was determined in vivo by the uptake of BrdU." (PMID 25624353, 2015). "Infecting untreated resting CD4+ T cells with Vpx-containing HIV Duo-Fluo I increased their infection levels over untreated cells infected with HIV Duo-Fluo I alone." (PMID 26067822, 2015). "At week 2 post-infection, the frequency and the number of CD4+CD25+Foxp3+ T cells was significantly lower in groups of mice receiving anti-CD25 when compared with IgG-treated mice." (PMID 26512987, 2015).